CRP (C-reactive protein)
Diseases named in the same sentence as CRP in open-access papers (continued):
Sharing a sentence is not in itself a finding about the gene and the disease.
infection (continued). "This study demonstrated that Presepsin and IL-6 are more reliable than CRP and PCT for the early detection of postoperative infections in HTx patients." (PMID 40806991, 2025). "Based on clinical follow-up data, patients were divided into low-level and high-level groups according to the changes in CRP and PCT levels, and clinical outcomes, including length of hospital stay and infection control, were analyzed." (PMID 40160471, 2025). "Inflammatory markers such as CRP, WBC, ESR pod3, PCT pod3, NLR pod3, and PLR pod3 were all significantly elevated in the infection group (P < 0.001)." (PMID 41488886, 2025). "Supplement 1 provides evidence of higher serological markers of inflammation and infection, WBC and CRP, in GERM(+) patients." (PMID 39828733, 2025). "We observed a correlation between CRP levels (as a marker of infection) and B-cell depletion, highlighting the importance of humoral immunity in the PTCY group for late infection control." (PMID 39562716, 2025). "To benchmark these findings, we evaluated two well-known clinical biomarkers of inflammation, C-reactive protein (CRP) and serum amyloid A (SAA1), which are commonly used to monitor infection progression." (PMID 39835799, 2025). "As expected, CRP and PCT levels demonstrated limited utility as early biomarkers for infection in this population." (PMID 40806991, 2025). "Complete blood count revealed elevated white blood cells (WBC)29x10^9/L and neutrophils (NEUT) percentage 84.9%, increased C-reactive protein (CRP) 7 mg/L, and elevated procalcitonin (PCT) 1.08 μg/L, suggesting a possible infection or inflammation." (PMID 40874431, 2025). "CBC analysis showed that phage treatment effectively suppressed infection-induced inflammation, as evidenced by lower WBC and C-reactive protein (CRP) levels compared to the mock-treated group, indicating reduced systemic immune activation." (PMID 40540524, 2025). "Secondarily, the incremental predictive performance of IL-6, CRP, white blood cell count (WBC) and procalcitonin (PCT) to a core model for predicting infection was evaluated." (PMID 40549692, 2025). "In all dogs, blood tests revealed signs of infection, including elevated white blood cell count (WBC), increased neutrophils, lymphocytosis, and high C-reactive protein (CRP)." (PMID 40564367, 2025). "Within the infection group, PTA patients showed significantly higher CRP (p = 0.036) and HMGB1 (p = 0.003) levels and lower kallistatin (p < 0.001) levels compared to PTC patients." (PMID 41153226, 2025). "The nomogram incorporating age, CRP, Wagner grade, LEAD, and PN parameters enables rapid DFIs screening, facilitating timely antibiotic initiation through early infection detection to enhance clinical management." (PMID 40604114, 2025). "When conducting subgroup analysis based on joint type and infection duration, all markers in the hip replacement patients showed significant increases in the PJI group (P < 0.01), among which CRP showed the largest difference (37.78 vs 8.67 mg/L, P < 0.001)." (PMID 41250763, 2025). "Although CRP levels rise at a slower rate compared to IL-1, TNF-α, and IL-6, they start to increase within 4–6 h after the onset of inflammation or infection and typically reach peak levels within 24–48 h." (PMID 40584620, 2025). "This study aims to evaluate the validity of a combined model involving PCT levels, C-reactive protein (CRP) levels, and white blood cell (WBC) for predicting early postoperative infection in pediatric patients undergoing open-heart surgery with CPB." (PMID 40373822, 2025). "The CRP, PCT, NC, and NLR levels in the infection group demonstrated an elevation in comparison to those in the non-infection group (P<0.05)." (PMID 41281267, 2025). "Many biomarkers, such as CRP and PCT, are widely used for infection diagnosis and monitoring in clinical practice." (PMID 40687411, 2025).
infection (continued). "CRP and PCT, with their moderate infection detection capacity, indirectly lead to significant costs by promoting unnecessary antibiotic use." (PMID 40471473, 2025). "C-reactive protein (CRP) is an acute-phase protein and the most commonly used biomarker in Swedish EDs to detect inflammation and infection." (PMID 40579468, 2025). "ICIS, CRP, and PCT were compared to routine clinical assessment to evaluate their effectiveness in predicting infection in critically ill patients." (PMID 40471473, 2025). "For infection discrimination, MDW yielded the highest AUC (0.843), followed by PCT (0.824) and CRP (0.775)." (PMID 41303127, 2025). "CRP, as a serum parameter for diagnosing PJI, has been supported by the European Bone and Joint Infection Society (EBJIS), the Musculoskeletal Infection Society (MSIS), and other societies." (PMID 41250763, 2025). "This combined biomarker model, incorporating PCT, CRP, and WBC, demonstrates promise for early postoperative infection prediction but requires further validation in larger and more diverse cohorts prior to clinical implementation." (PMID 40373822, 2025). "Routine testing includes complete blood counts, stool cultures, infection screening, fecal calprotectin, erythrocyte sedimentation rate (ESR), and C-reactive protein (CRP), which help exclude infectious etiologies and quantify systemic inflammation." (PMID 41552252, 2025). "For infection identification, PCT again showed the best performance (AUC of 0.849), with MDW (0.816) and CRP (0.796) yielding slightly lower AUCs." (PMID 41303127, 2025). "C-reactive protein (CRP) and procalcitonin (PCT) are useful serum inflammatory biomarkers which can aid the diagnosis of serious infection." (PMID 39621113, 2025). "The Intervention (I) consists of laboratory-based biomarker assessments (CRP, PCT, and WBC) for early detection of infection." (PMID 40342430, 2025). "Over this period, blood markers including C-reactive protein (CRP) and erythrocyte sedimentation rate (ESR) are monitored to assess response to infection." (PMID 40657213, 2025). "First, all positive mNGS results must be strictly correlated with definitive clinical evidence of infection, such as progressive pulmonary infiltrates on imaging and elevated inflammatory markers like procalcitonin (PCT) and C-reactive protein (CRP)." (PMID 41278474, 2025). "Regarding laboratory test variations, there was a decrease in mean lactate levels and an increase in mean C-reactive protein (CRP) levels between the burn injury and the first documented infection." (PMID 40802437, 2025). "Standard laboratory parameters such as white blood cell (WBC) counts, C-reactive protein (CRP) levels, and procalcitonin (PCT) levels are used in clinical practice to monitor inflammation and infection status in COPD patients." (PMID 40282960, 2025). "Even with the rapid development of high-throughput technologies today, most physicians still rely solely on clinical symptoms, full blood count (FBC), CRP, and PCT for diagnosing the type of infection in febrile children." (PMID 40843077, 2025). "Hence, high CRP levels may indicate a more severe infection or complications." (PMID 40373091, 2025). "Some of the laboratory investigations indicated an active infection by measuring the white blood cell (WBC) and C-reactive protein (CRP), which was high, and the erythrocyte sedimentation rate (ESR), which was slightly elevated." (PMID 40130139, 2025). "Of these, fifty-two (89.7%) HCW’s found CRP POCT to be “very important” for guiding antibiotic treatment in neonates and children with signs of infection and five (8.6%) found it to be “somewhat important”." (PMID 41433251, 2025). "In model 2, when combining the PCT level with CRP level or WBC count on POD 3, this combination had a significant predictive value for postoperative infection." (PMID 40373822, 2025).
infection (continued). "This highlights the need for more education as well as practical tools, such as serial CRP POCT, to assist in a more rational antibiotic use in childhood infections." (PMID 41433251, 2025). "In the 58 patients who developed a suspected or confirmed bacterial infection, plasma calprotectin predicted such infections significantly better than what WBC and PCT did, and marginally better than what CRP did." (PMID 40650251, 2025). "Compared to CRP and SAA, SF has a delayed response, generally rising 24-48 h after infection and lasting for a long time." (PMID 40171163, 2025). "The leukocyte activation markers nCD64 and mCD169 offer significant advantages over conventional biomarkers (e.g., WBC, CRP, and PCT) in infection diagnosis." (PMID 41159746, 2025). "Infection markers such as erythrocyte sedimentation rate (ESR), high-sensitivity C-reactive protein (CRP), calcitonin, interleukin-6 (IL-6), and ferritin were elevated." (PMID 41341819, 2025). "The Alb-to-Glb ratio (AGR), which combines Alb and Glb, and the CRP-to-Alb ratio (CAR), which combines CRP and Alb, have been reported to be useful for diagnosing infections after total hip arthroplasty." (PMID 40943760, 2025). "The combination of PCT > 4.15 ng/ml, CRP > 22.03 mg/l, and WBC > 15.3 × 103/μl predicted infection with a hazard ratio 9.66 times (2.94–31.72) higher than PCT > 4.15 ng/ml alone (p < 0.05)." (PMID 40373822, 2025). "The CRP, PCT, and NLR levels in the infection group were more significant than those in the non-infection group (p < 0.05)." (PMID 40026526, 2025). "Therefore, this study, derived from our author's thesis, aimed to investigate in which cases elevated CRP should or should not be associated with infection in this patient population and to determine a cutoff value that could predict the presence of infection." (PMID 40125102, 2025). "It has been known that presepsin expression is infection-specific compared with conventional biomarkers of PCT, CRP, and lactate, with a shorter response time after onset and shorter half-life in blood." (PMID 41153245, 2025). "If infection is suspected, inflammatory markers should be analyzed, including erythrocyte sedimentation rate (ESR) and C-reactive protein (CRP)." (PMID 39931591, 2025). "C-reactive protein (CRP) and white cell count (WCC), as indicators of inflammation and infection, were within the normal range and similar for both MFI and UI." (PMID 41155459, 2025). "Model 3, combining PCT, CRP, and WBC, had the best predictive ability for postoperative infection with an AUC of 0.81 (95 % CI: 0.69–0.93) (p = 0.002)." (PMID 40373822, 2025). "Beyond CRP, alternative biomarkers such as PCT and NLR have emerged as potential adjuncts for infection monitoring." (PMID 40342430, 2025). "Pentraxin-3 (PTX-3) is a pattern recognition molecule in the same protein family as C-reactive protein (CRP) and is produced in various extrahepatic tissues and blood cells in response to inflammation and infection." (PMID 40008348, 2025). "Despite normalization of ESR and CRP, ongoing FDG uptake at the petrous apex raised suspicion of subclinical infection and led to the continuation of suppressive therapy." (PMID 40709020, 2025). "Elevated levels of CRP (4.66 mg/dl ± 4.08; 2.69 mg/dl ± 2.62) and PCT (1.08 ng/ml ± 2.04; 0.37 ng/ml ± 0.60) were also observed in patients with infections (p = 0.009 and 0.005 respectively)." (PMID 41354872, 2025). "ICIS outperformed CRP and PCT in identifying infection in critically ill patients across different ICU settings on the first day in the ICU." (PMID 40471473, 2025). "Extracted information included first author, year of publication, country, study design, sample size, type of GI surgery, timing and thresholds of CRP/NLR measurements, and outcomes related to postoperative infections." (PMID 41018345, 2025).
infection (continued). "Key parameters of infection (IL-6, TNFa, D-dimer, CRP and CD4+ T cell counts) were correlated (Spearman) with lipid concentrations at critical time points of infection and treatment." (PMID 40129985, 2025). "The postoperative levels of CRP and PCT in the infection group were significantly higher than in the control group (P < 0.05)." (PMID 40160471, 2025). "Patients with CRP ≥ 145 were older, had longer ICU stays, higher Apache II and SOFA scores, greater need for mechanical ventilation, higher incidence of AKI and infections, and lower survival rates." (PMID 41303205, 2025). "Previous studies have identified high sensitivity for WBC, CRP, and ESR in detecting pyogenic spondylitis and other infections." (PMID 40943760, 2025). "Activation of the GLP-1 receptor inhibits the expression of inflammatory cytokines such as IL-6, IL-1β, TNF-α, and C-reactive protein (CRP) and promotes a milder course of infection." (PMID 41465455, 2025). "Patients in the high CRP and PCT group had a significantly longer hospital stay compared to the low-level group, and infection control rates were lower." (PMID 40160471, 2025). "Recent studies have identified D-Dr as a specific marker of the fibrinolytic system and an indicator of the inflammatory response and severe infection, demonstrating positive correlations with WBC, CRP, LDH, and ESR." (PMID 39981208, 2025). "The findings of this study highlight the challenges 438 associated with the use of traditional inflammatory markers, such as CRP and PCT, for 439 the early detection of postoperative infections in HTx patients." (PMID 40806991, 2025). "Traditional clinical markers such as erythrocyte sedimentation rate (ESR) and C-reactive protein (CRP) objectively reflect inflammation levels; however, they are easily affected by various factors, including infection and acute stress." (PMID 41488659, 2025). "Laboratory evaluations, including complete blood count (CBC), high-sensitivity C-reactive protein (hs-CRP), and interleukin-6 (IL-6), were performed at baseline, 1 month, and 6 months, or upon clinical suspicion of infection." (PMID 41254792, 2025). "Marked reductions in infection biomarkers, including procalcitonin (PCT) and C-reactive protein (CRP), coupled with enhanced granulation tissue formation, corroborate ozone therapy’s efficacy in microbial eradication and tissue regeneration." (PMID 40565762, 2025). "Inflammatory markers such as CRP and erythrocyte sedimentation rate (ESR) are traditionally used for infection workup in clinical practice." (PMID 40363957, 2025). "Traditionally, inflammatory biomarkers, such as CRP and PCT, have been used to detect infections in various clinical settings." (PMID 40806991, 2025). "The AUC of ROC analysis for the prediction of infection on the first day in ICU was highest for ICIS, followed by PCT and lowest for CRP." (PMID 40471473, 2025). "Compared with traditional markers such as procalcitonin (PCT) and C-reactive protein (CRP), presepsin increases significantly earlier after the onset of infection." (PMID 41169360, 2025). "On the fourth day post-infection, K. pneumoniae infection resulted in a significant increase (P < 0.05) in biochemical parameters: ALT, AST, total protein, creatinine, and CRP compared to the neutral control." (PMID 40777688, 2025). "Regular monitoring of infection markers, such as CRP, ESR, PCT, or presepsin, is important for early detection of latent or recurrent infections." (PMID 40171003, 2025). "Beyond infection control, IMMUNEPOTENT CRP has been shown to modulate cytokine expression and reduce inflammation in clinical settings such as third molar extractions." (PMID 41394149, 2025). "CRP, procalcitonin, leukocyte number, thrombocytes, HDL, LDL, bilirubin, albumin, creatinine, MELD score, and AST of genotype 3 infection were similar to other genotypes (p > 0.05 for all)." (PMID 41301814, 2025).
infection (continued). "Two weeks after starting broad-spectrum antibiotics, including piperacillin–tazobactam, he developed symptoms of right chest pain and cough and showed a decline in infection-related marker values, with a WBC count of 15.2 × 109/L and CRP level of 7.46 mg/L." (PMID 40727278, 2025). "This suggests concomitant actions of CRP and the lytic MAC on the parasite blood stages, i.e., P. chabaudi-parasitized erythrocytes and free merozoites, during the crisis phase of infection." (PMID 40243929, 2025). "Logistic regression models were univariate, evaluating hs-cTn24h, hs-cTn48h, CRP, ESR, and leukocytes individually as predictors of infection." (PMID 41008500, 2025). "A structured search was conducted across PubMed, MEDLINE, Embase, and Cochrane Library, using a combination of MeSH terms and keywords related to CRP, PCT, WBC, NLR, SSIs, and postoperative infections." (PMID 40342430, 2025). "C-Reactive protein (CRP) is an acute inflammation-related protein, and its abundance increases up to 1,000-fold in response to infection or inflammation." (PMID 39886481, 2025). "For infection identification, MDW demonstrated the highest AUC (0.853), followed by PCT (0.819) and CRP (0.771)." (PMID 41303127, 2025). "This meta-analysis aimed to evaluate the predictive value of two widely available inflammatory biomarkers, C-reactive protein (CRP) and neutrophil-to-lymphocyte ratio (NLR), in forecasting postoperative infections in patients undergoing GI surgery." (PMID 41018345, 2025). "The findings of this study highlight the challenges associated with the use of traditional inflammatory markers, such as CRP and PCT, for the early detection of postoperative infections in HTx patients." (PMID 40806991, 2025). "While markers such as C-reactive protein (CRP) and interleukin-6 (IL-6) have been extensively studied in relation to the atherosclerotic process, procalcitonin (PCT), a known marker of infection, has recently garnered attention in this context." (PMID 40963340, 2025). "CRP and PCT are known to be traditional inflammatory markers commonly used in clinical practice to assess infections and predict prognosis." (PMID 40521830, 2025). "The infection stress indicators (PCT, β-EP, and CRP) of each group in POD-7 and POD-14 were significantly reduced compared to POP levels." (PMID 39927282, 2025). "Since infections are a common precipitating factor for DKA, inflammatory markers like C-reactive protein (CRP) and white blood cell (WBC) count should be routinely assessed." (PMID 41149081, 2025). "Furthermore, there is a certain degree of incorporation bias since the infection score that we generated on the basis of six criteria contained aspects that can be regarded as part of the clinically accepted reference standard, e.g., a CRP above a certain threshold." (PMID 38963607, 2025). "CRP and ESR are important indicators for evaluating inflammation and identifying postoperative infections." (PMID 41431054, 2025). "We stopped using antibiotics when the symptoms of infection were resolved and laboratory test results, such as ESR and CRP, improved." (PMID 40423059, 2025). "Acute-phase proteins (APPs), such as C-reactive protein (CRP), are produced by hepatocytes upon stimulation by pro-inflammatory cytokines released from macrophages and other cells during infection or tissue damage." (PMID 41463874, 2025). "C-reactive protein (CRP) and procalcitonin (PCT) are widely used biomarkers for the detection and monitoring of infections in septic patients." (PMID 40471473, 2025). "CRP and CSF protein were found to be significantly higher in the RVPS infection group than in the SVPS infection group (<0.026 and <0.001, respectively)." (PMID 39858363, 2025). "By incorporating a comparative analysis of multiple biomarkers (CRP, PCT, WBC, and NLR) across diverse surgical fields, this review provides a broader perspective on post-surgical infection detection than previous single-biomarker studies." (PMID 40342430, 2025).